CD4 (CD4 molecule)
Diseases named in the same sentence as CD4 in open-access papers (continued):
Sharing a sentence is not in itself a finding about the gene and the disease.
gastric cancer (continued). "In order to evaluate the miR-155 expression in gastric mucosa, we cultivated gastric cancer AGS cells and isolated mucosal CD4+ immune cells from antral gastric biopsies of patients with chronic gastritis." (PMID 33857171, 2021). "TMA sections were developed to visualize CD3, CD4, CD8, FOXP3, GARP, and CK simultaneously on a cohort of gastric cancer samples." (PMID 34421887, 2021). "We further found the expression of GARP in CD4+ T cells and analyzed that GARP+CD4+ T cells play a significant role in the prognosis of gastric cancer." (PMID 34421887, 2021). "In patients with advanced gastric cancers, CD45RA- FoxP3+ CD4+ effector Tregs cells expressing VEGFR-2 are present in higher frequency in TIL than in PBMC." (PMID 33854498, 2021). "In summary, we show that gastric cancer exosomes produce an immunosuppressive microenvironment through decreasing CD8+ T cell and NK cell number, increasing CD4+T cell number and recruiting MDSC." (PMID 32901082, 2020). "Moreover, it should be emphasised that the high counts of GATA3+ lymphocytes in gastric mucosa may be the consequence of a IL-4 driven T-helper-2-cell differentiation of CD4+ T cells, a mechanism described in the context of H. pylori infection and that could influence gastric cancer pathogenesis." (PMID 32575504, 2020). "Overall, our results suggest that exosomes from a poorly differentiated gastric cancer cell line MKN-45 are more capable than that of MKN-28 and SGC-7901 cells to induce CD4+ T cell with CD62lowCD44hi phenotype and recruiting of MDSC." (PMID 32901082, 2020). "It was found that PCOLCE was closely related to B cells, CD4 + T cells, CD8 + T cells, neutrophils, macrophages, dendritic cells and other immune infiltration in gastric cancer." (PMID 33392251, 2020). "The frequencies of PD‐1+ CD4+ T cells and PD‐1+ CD8+ T cells are reportedly significantly higher in gastric cancer patients than in healthy individuals, and the frequency of PD‐1+ effector Tregs is also known to increase." (PMID 32529780, 2020). "We found that Helios is expressed more in CD4+ T cells and little in CD8+ T cells in infiltrated lymphocytes in gastric cancer." (PMID 32927747, 2020). "CD4+T cells (Th17) and CD8+ IL-17 producing cells T cells (Tc17) have reported in patients with gastric cancer." (PMID 31024835, 2019). "Using TMA of 183 gastric cancer patients and IHC analysis, we identified infiltrating CD3+ (TIL), CD4+ regulatory and CD8+ cytotoxic T cells." (PMID 31596872, 2019). "We confirmed that the expression levels of peripheral and tumor‐infiltrating DC2s, CD4+/CD8 + T cells, Foxp3 + Tregs, and IDO were correlated with each other as well as with clinicopathological characters and gastric cancer prognosis." (PMID 31631566, 2019). "Ex vivo, gastric cancer Bregs suppressed IFN-γ and TNF-α secretion by CD4+ cells and mediated conversion of CD4+ cells to CD4+FoxP3+ Tregs via TGF-β signaling." (PMID 27437104, 2016). "We investigated the frequencies of TILs including CD8+ T cells, CD45+CD4+CD25± FOXP3+ Tregs, CD45+CD11b+ CD14+ HLA−DR− MDSCs in 28 gastric cancer tissues by using multicolor flow cytometry." (PMID 26799288, 2016). "In this study, we enrolled 112 gastric cancer patients, immunofluorescence was used to evaluate the colocalization of CD3, CD4, CD56, CD20, CD68, and mast cell tryptase (MCT) with IL-17." (PMID 25197971, 2014). "More importantly, they abrogated the immunosuppression induced by CD4+CD25+ Treg cells and induced the cytotoxic function of CD8+ αβ T cells from patients with gastric cancer." (PMID 24741609, 2014). "Thoracic and gastric cancer patients: Systematic review and meta-analysis identified EEN as significantly increasing serum albumin and prealbumin levels, along with immune markers CD3 + and CD4 + lymphocytes." (PMID 41393937, 2025).
gastric cancer (continued). "CD4 + /CD8 + T cells have been reported to partially reflect the infiltration of lymphocytes in gastric cancer tissues, predict the response to immunotherapy to a certain extent, and ultimately affect the tumor progression and survival of gastric cancer." (PMID 39088070, 2024). "The goal of this study was to determine whether the DCE-MRI-based noninvasive prediction model could predict the infiltration of CD3, CD4, and CD8 T-cell expression levels in advanced gastric cancer." (PMID 38549936, 2024). "Through analysis, we found that the high expression of MCU in gastric cancer affects the expression of MHC molecules, which in turn may reduce immature B and T Tregs while increasing memory resting CD4+ T cells, activated dendritic cells, and neutrophils." (PMID 38737905, 2024). "Two TMA slides, each containing 90 pairs of gastric cancer and corresponding paracancerous tissues, were selected for mIF analysis of TOB1, CD8, CD4, FOXP3, CD20, CD68, and CD66b to investigate the profiles of TOB1 protein expression and immune cell infiltration in gastric cancer." (PMID 38617839, 2024). "The correlation analysis between Treg cell signature genes (CD4, CD25 and FOXP3) and CD8A in The Cancer Genome Atlas (TCGA) database containing 415 gastric cancer samples revealed that the expression of CD4, CD25 and FOXP3 was positively correlated with CD8A expression respectively." (PMID 37208608, 2023). "The high naïve CD4+/CD8+TIL ratio also represented a poor prognostic factor in patients with NCT‐NSCLC, which was consistent with previous study on operations for NSCLC and gastric cancer." (PMID 36789099, 2023). "Likewise, a previous report indicated that FoxM1 overexpression enhanced the number of CD4+CD8+ Treg cells and Ki67 protein levels, to strengthen the immune escape of gastric cancer." (PMID 36301031, 2022). "Hence, we sought to investigate the involvement of CXCR5+CD4+ Tfh cells and CD19+CD24hiCD38hi Breg cells in gastric cancer." (PMID 36339942, 2022). "Finally, the exclusion scores of 30 gastric cancer patients were compared to the ratio of cell densities at the CT versus IM of the CD3+, CD4+ or CD8+ cells." (PMID 35595859, 2022). "In addition, we further carried out multivariate analysis with these important factors, and the results showed that CD3D, CD4, and CD8 were independent prognostic factors for gastric cancer in both the univariate and multivariate analyses." (PMID 35719985, 2022). "CD8+ T cells and activated CD4+ memory T cells correlated with each other well, and both of them were inversely correlated with the terms “TGFβ signaling pathway” and “GAP junction”, confirming an immune-suppressing role of these pathways in gastric cancer." (PMID 34177954, 2021). "The results illustrated that TAMs (31.94%), resting memory CD4+ T cells (16.49%), CD8+ T cells (13.45%) and Treg cells (6.81%) were abundant in gastric cancer, whereas naive CD4+ T cells (0.01%), eosinophils (0.43%), δγ T cells (0.34%), monocytes (0.77%) and memory B cells (1.18%) were sparse." (PMID 32969836, 2020). "The proportion of naive CD4+ T cells increased in stage IV tumors, but there was no significant influence on the OS of gastric cancer patients." (PMID 32969836, 2020). "As an auxiliary therapy for gastric cancer, JPBS combined with chemotherapy improved the efficiency of clinical curative effect, increased KPS score, increased the levels of CD3+, CD4+, CD4+/CD8+, NK+, and macrophages, and reduced the level of CD8+ and the rates of decline of WBC, PLT, and Hb." (PMID 29675052, 2018). "However, the present results are consistent with our recent report that a higher number of Tregs among CD4+ T cells correlated with increased OS and DFS and it was an independent prognostic factor for gastric carcinoma." (PMID 28076847, 2017).
gastric cancer (continued). "In the qPCR analysis, A2PP and truncated peptides A2PP-Nd4, Nd8, Nd12, Cd4, Cd8, and Cd12 reduced M. hyorhinis infection in gastric cancer cells, but A2PP-Nd16 and A2PP-Cd16 failed to decrease M. hyorhinis infection." (PMID 26812398, 2016). "Furthermore, CD24hiCD38hiBregs convert CD4+CD25− effector T cells into CD4+FoxP3+ Tregs, which are dependent on TGF-β1 in gastric cancer." (PMID 26378021, 2015). "Some studies have found decreases in both CD4+ and CD8+ lymphocytes following major surgery, while other studies on gastric cancer patients revealed a significant decrease in numbers of CD8+ but not CD4+ lymphocytes although our study only investigated bulk lymphocyte numbers." (PMID 19138398, 2009). "Moreover, the results of subgroup analysis showed that SJZD could increase the CD3+, CD4+, and CD4+/CD8+ of patients with esophageal or gastric cancer, and decrease the CD8+ of esophageal cancer." (PMID 39928794, 2025). "Gastric cancer and paracancerous tissue specimens from surgically resected gastric cancer patients were collected to construct tissue microarrays, and immunohistochemistry was used to detect the expression of SFRP4, PD-L1, CD3+T, CD4+T, and CD8+T in these microarrays." (PMID 35847366, 2022). "Therefore, we further detected the expression of CD3, CD4, CD8 and PD-L1 in the tumor tissues of the included gastric cancer patients and evaluated their relationship with CD3D to explore the regulatory role of CD3D in the immune microenvironment of gastric cancer." (PMID 35719985, 2022). "The B cells, CD8 T cell, and dendritic cell infiltration scores of the PLA2R1 gene had no statistical significance in gastric cancer, while the infiltration scores of CD4 T cells and neutrophils were significant in gastric cancer, and macrophages were extremely significant." (PMID 36140749, 2022). "In a Balb/c nu/nu tumor transplantation model, CD4+ T cells are reported to upregulate PD-L1 expression in gastric cancer-derived MSCs (GC-MSCs) via the p-STAT3 signaling pathway, and to activate the PD-1/mTOR signaling pathway, thereby promoting gastric cancer growth." (PMID 36439438, 2022). "And in the gastric cancer groups, the proportion of CD4− MAIT cells without chemotherapy (79.2%, p = 0.023) was lower than that with chemotherapy (89.8%), the absolute amount of CD4− MAIT cells with chemotherapy (2.23, p = 0.036) was also lower than that without chemotherapy (0.67)." (PMID 33422137, 2021). "Immunocompetent cells and humoral immune factors, including DC2s, CD4+/CD8 + T cells, Foxp3 + Tregs, and IDO, interact with each other to compose a complex community of tumor immune microenvironment, ultimately affecting tumor progression and survival of gastric cancer." (PMID 31631566, 2019). "Third, CD4 and CD74 may be used as markers to predict the prognosis of colon and gastric cancer." (PMID 27323782, 2016). "In vivo experiments further revealed that KHSRP silencing markedly increased the infiltration of CD4+, CD8+, Granzyme B+, IFN-γ+, and TNF-α+ cells within the tumor, suggesting that KHSRP could serve as a potential prognostic marker and therapeutic target for gastric cancer." (PMID 39866240, 2025). "Notably, the enrichment of endothelial cells, macrophages, and cancer-associated fibroblasts in diffuse gastric cancer and their lower proportions in CD4+ and CD8+ T cells may contribute to an immunosuppressive milieu and, consequently, poorer prognosis compared to intestinal-type gastric cancer." (PMID 41584584, 2025). "Consistent with previous research, we observed a significant increase in the infiltration of CD4 T cells, CD8 T cells, and NK cells in KDM3A‐ablated tumors, suggesting that targeting KDM3A could be a promising strategy for reversing the non‐MSI TME in gastric cancer." (PMID 39031630, 2024).
gastric cancer (continued). "In our investigation of the immunological microenvironment in gastric cancer (GC) patients, we observed strong correlations between CLDN18.2 expression levels and CD4 + T cells, CD8 + T cells, and B cells according to the TISIDB database analysis (all p < 0.05)." (PMID 37582713, 2023). "Nevertheless, there has been no systematic analysis of the effect of CD4+ memory T cells in gastric cancer (GC)." (PMID 33816214, 2020). "Studies addressing the relationship between peripheral blood CD4 + T cells, CD8 + T cells, Treg cells, and B cells and the effectiveness and progression-free survival of immunotherapy for advanced gastric cancer are lacking." (PMID 38491354, 2024). "Kaplan–Meier survival analysis showed that the expression of CD4 and CD8 was correlated with the survival of gastric cancer patients, while the expression of CD3 and PD-L1 was not." (PMID 35719985, 2022). "We estimated the correlation of FNDC5 expression with 22 immune cells based on signature expression data from gastric cancer patients and found a significant negative correlation between FNDC5 and CD4+ memory-activated cells by using the CIBERSORT algorithm." (PMID 36386179, 2022). "However, no study has focused on determining the extent of CD3+, CD4+, and CD8+ T-cell infiltration in advanced gastric cancer." (PMID 38549936, 2024). "In non-CVID patients, there was an increase of Foxp3+, GATA3+, CD4+ and CD8+ T cell counts as well CD20+ B cell counts when the non-neoplastic mucosa distant from tumour was compared to gastric cancer (p = 0.001; p = 0.002; p = 0.006; p = 0.003; p = 0.004, respectively)." (PMID 32575504, 2020). "Another finding in this study is that CD4 and CD74 may be used as markers to predict the prognosis of colon and gastric cancer, but not the markers for cancer stem cell." (PMID 27323782, 2016). "However, no obvious trend was found among CD44, CD4, and CD74 mRNA in gastric cancer." (PMID 27323782, 2016). "Besides, after co-culture with gastric cancer cell HGC27, the percentage of total CD8+ T cells and CAR+ T cell in CD8+ T cells was not changed significantly in CAR-ss-T, suggesting the existence of IL-15/IL-15Rα did not affect the proportion of CD8+ and CD4+ T cells." (PMID 38368374, 2024).
inflammatory bowel disease (271 papers, 2006 to 2026). A spectrum of small and large bowel inflammatory diseases of unknown etiology. "Activation of CD4+ T cells is a key feature in inflammatory bowel disease, and loss of Piezo1 in CD4+ T cells promotes Th1 and Th17 cell polarization." (PMID 37781915, 2023). "ETS1 has also been linked to CD, as it is highly expressed in CD4+ T-cells from patients with inflammatory bowel disease and promotes Th1-driven mucosal inflammation through cold-inducible RNA binding protein (CIRBP)." (PMID 37048094, 2023). "Inflammatory bowel disease (IBD) is an immunological disease associated with CD4+ T cell activation in the intestines." (PMID 32332834, 2020). "In the models coming closest to aGvHD, that is, those for Inflammatory Bowel Disease, protection from disease was associated with increased Treg frequencies among CD4+ T cells 35 as was the case in our study." (PMID 27980780, 2016). "The mutant rats showed a high incidence of inflammatory bowel disease, which was associated with skewed cytokine secretion by effector CD4 T cells towards Th2 and Th17 and with impairment of the suppressive activity of the regulatory CD4 T cells (Treg)." (PMID 22275874, 2012). "Notably, active eosinophils are enriched in the lamina propria of a small cohort of patients with inflammatory bowel disease, and are closely associated with CD4+ T cells." (PMID 36509106, 2023). "Moreover, Th1 cells and the other subset of CD4 effector T cells, Th17 cells, have been reported to be associated with autoimmune diseases, such as inflammatory bowel disease (IBD), rheumatoid arthritis, and (multiple sclerosis) MS." (PMID 36324680, 2022). "IL-26 is associated with the activation of Th17 and CD4+ IL-22+ T-cells; it also plays a role in inflammatory bowel disease, which may associate with the extra-pulmonary gastroenteritis manifestation during SMPP." (PMID 36618370, 2022). "The results of a multicenter phase I/IIa clinical trial indicate that the change in the balance between Foxp3 + CD4 + Treg cells and T effector cells in the intestinal microenvironment may be the cause of inflammatory bowel disease." (PMID 33553436, 2021). "These animals were also shown to develop a spontaneous inflammatory bowel disease (IBD) associated with increased abundance of CD4+ T cells expressing the pro-inflammatory cytokines IL17, interferon gamma (IFNγ), and tumor necrosis factor alpha (TNF⍺) in the colonic lamina propria." (PMID 32598378, 2020). "The up-regulated expression of the Ca2+-activated K+ channel KCa3.1 in inflammatory CD4+ T cells has been implicated in the pathogenesis of inflammatory bowel disease (IBD) through the enhanced production of inflammatory cytokines, such as interferon-γ (IFN-γ)." (PMID 30262728, 2018). "CD4+ T cell-derived IL-22BP demonstrated a pathogenic role in inflammatory bowel disease (IBD)." (PMID 28770173, 2017). "Transfer of CD4+CD45RBhigh expressing T cells into an immunodeficient mouse induces chronic intestinal inflammation and this population of cells is conventionally used to induce inflammatory bowel disease in mice, illustrating their pathogenic potential." (PMID 22428018, 2012). "Excessive CD4+ T cell responses drive inflammatory bowel disease (IBD), yet the transcriptional mechanisms underlying their dysfunction remain incompletely understood." (PMID 41347630, 2025). "In the case of inflammatory bowel disease (IBD), it has been found that approximately half of the risk SNPs are located in the SE regions of CD4 T cell activation." (PMID 40672386, 2025). "In the context of inflammatory bowel disease (IBD), approximately half of the associated SNPs have been identified within the SE-regulated regions of CD4+ T-cells." (PMID 38542080, 2024). "Inflammation associated with inflammatory bowel disease (IBD) has been reported to be closely associated with aberrant immune response elicited by CD4 T cells and dendritic cells." (PMID 36388363, 2022).